LINC00595 (long independently transcribed non-coding RNA 595)
Synonyms: C10orf101; LOC105378375; LINC00856
Gene: Long non-coding RNA gene on chromosome 10 (78,179,167 to 78,675,109, forward strand). Ensembl gene ENSG00000230417.
Diseases named in the same sentence as LINC00595 in open-access papers:
LINC00595 is named in the same sentence as 2 diseases in open-access papers, as found by Europe PMC text mining. Sharing a sentence is not in itself a finding about the gene and the disease. The quoted sentences say what the papers report.
thyroid cancer (1 paper, 2018). "Moreover, some of those dysregulated lncRNAs genomic loci contains copy number amplification or deletion, such as LINC01354, LINC01341, LINC00595, and LINC01519, suggesting that genomic alterations might involve in part of these lncRNAs dysregulation in thyroid cancer." (PMID 29923329, 2018).
LINC00595 also shares sentences with these, for which no sentence is quoted: infection (1 paper).